IL10 (interleukin 10)
Diseases named in the same sentence as IL10 in open-access papers (continued):
Sharing a sentence is not in itself a finding about the gene and the disease.
infection (continued). "infections resulted in a significant elevation in IL-10 level (p < 0.01) compared to S. digitata infections." (PMID 36145411, 2022). "A dose dependent production of pro-inflammatory (TNF, IL-6 and IL-12p40) and anti-inflammatory (IL-10) cytokines in BM-DCs supernatants was observed after infection with all leptospires." (PMID 35812397, 2022). "We noticed a significantly lower population of IFN-γ expressing CD4+ cells in IL-10+ Breg recipient mice in comparison to the control group of animals 9 days post infection." (PMID 35625397, 2022). "Among Th2 cytokines in the mouse lung, we found that the levels of all four marker cytokines (IL-4, IL-6, IL-10, and IL-13) progressively increased with infection time; similarly, the levels of IL-6, IL-10 and IL-13 were upregulated in the mouse brain." (PMID 35617354, 2022). "Interleukin-10 (IL-10), is an important anti-inflammatory cytokine well known to limit the excessive inflammatory immune response induced due to infection by pathogen and thereby have protective effect on host." (PMID 35625397, 2022). "In our study, infection with B.1.351 elevated the levels of IFN-γ, TNF-α, IL-13, and IL-10, whereas infection with GD108 elevated the level of IL-17 in macaques." (PMID 36069561, 2022). "IL-10 is a key cytokine that regulates the intensity and duration of the immune response to infection studies have shown that its high level is related to the risk of children suffering from ALL." (PMID 35721208, 2022). "Interleukin 10 is an anti-inflammatory cytokine which is elevated at early stages of infection, preceding pro-inflammatory cytokines elevation." (PMID 35839254, 2022). "In the lethal P. berghei ANKA (PbA) infection model, administration of recombinant IL-10 during infection prolongs survival." (PMID 35631044, 2022). "In contrast, the production of IL-8 (p = 0.0277) and IL-10 (p = 0.0449) was significantly increased in patients with ongoing infection, as compared to recovered patients and healthy donors." (PMID 35911747, 2022). "Regarding the opposite trends of these two T-cells, an interrelationship has been suggested, with CD4+ regulatory T-cells producing IL-10 to promote memory CD8+ T-cell maturation during infection regression." (PMID 36039499, 2022). "Next, interleukin-10 (IL-10) production was observed by Luminex at 3rd and 10th day post infection to gain insight into the immune dynamics." (PMID 35109868, 2022). "Although it is a crucial cytokine in limiting excessive immune activation, IL-10 exacerbates infection by preventing the clearance of H. capsulatum." (PMID 36145686, 2022). "Ratios of IL-10 to TNFα and IL-10 to INFγ show a persistent anti-inflammatory cytokine environment during the chronic stage of infection." (PMID 36420267, 2022). "IL-10 responses tended towards an increase during later stages of infection, which was particularly evident in the MLNs and liver." (PMID 35958580, 2022). "After infection with Aeromonas hydrophila, we found that the IL-10 and IL-11 expression levels were upregulated in each group, while TLR-4, MYD88, and TNF-α were down regulated." (PMID 36139830, 2022). "IL-10 has been considered to have potent broad-spectrum anti-inflammatory activity, which has been clearly confirmed in various infection, inflammation, and cancer models." (PMID 35299759, 2022). "Infection with Pb K173 resulted in a build-up of IL-10-producing leucocytes, mostly CD4+ and CD8+ αβ T cells, when compared to NI mice." (PMID 35768411, 2022). "At 4 weeks post-infection (PI), 72 colonies were isolated from 12 WT mice, and 82 colonies were isolated from 15 Il10−/−/− mice." (PMID 35289715, 2022). "A relevant data in this model of infection is the production of IL-10 by keratinocytes in late post-infection times with yeasts or conidia." (PMID 35628694, 2022).
infection (continued). "How does miR-146a ensure a high IL-10 expression in treated macrophage to polarize them to have an anti-inflammatory response pathway—a prelude to the infection niche establishment?" (PMID 35210329, 2022). "In late post-infection, cytokine production was observed with immunoregulatory activity, IL-10, and growth factors, G-CSF and GM-CSF." (PMID 35628694, 2022). "Together, these data show that SDR in old mice increased expression of IL-10 mRNA and decreased expression of IFN-γ mRNA at 60 days post infection, which is consistent with the loss of control of the M.tb infection in these mice." (PMID 36189368, 2022). "We noted that IL-10 were detected in very few patients during the acute phase of infection, in agreement with our previous study." (PMID 35456119, 2022). "Plasma IL-10 during chronic infection (d58 p.i.)was elevated relative to pre-infection (d–20; 19.96 ± 2.481 pg/mL vs. 8.32 ± 0.7849 pg/mL)." (PMID 35230978, 2022). "The presence of 4b in the nucleus in MERS-CoV-MA-WT in vivo infection partially changed the pro-inflammatory cytokine profile, by upregulating IFNß, IL-6 and IL-10, as compared to MERS-CoV-MA-mNLS, which expressed a cytoplasmic 4b." (PMID 36129908, 2022). "Increased IL-1rα and IL10 expression prior to infection can compromise early immune response to HIV and result in reduced CD4:CD8 ratio." (PMID 35165387, 2022). "We conclude that the immunodepression observed following infection with SARS-CoV-2 is possibly driven by IL-10." (PMID 35572964, 2022). "Following infection with Citrobacter 7 days earlier, the expression of transcripts for proinflammatory cytokines Il1β, Il12, and Il18 and for immunoregulatory Il10 was increased." (PMID 35140345, 2022). "Interleukin (IL)-10 is an immune-regulatory cytokine which plays an immunosuppressive role during infection." (PMID 36310865, 2022). "These IL-10+ Breg cells were adoptively transferred (5 × 106 cells) into naive mice followed by infection with the Py 17XL strain." (PMID 35625397, 2022). "The expressions of il10, nos2 and the ISGs isg15, and mx1 were only upregulated in tlr2−/− macrophages following infection, indicating that TLR4 controls the levels of these M(Kp) markers." (PMID 36337046, 2022). "This strengthens the importance of the interleukin-10/NFκB signalling pathway axis in maintenance of gut health and response to damage, inflammation, and infection." (PMID 36290283, 2022). "Corresponding to BECs, IFNγ increases LEC activation, while IL-10 downregulates LEC activation upon infection." (PMID 35789215, 2022). "Intracellular IL-10 CD8+ T cell and extracellular IL-10 T-cell responses were higher in CHB than in OBI (P = 0.012) or HBV resolved infections (P < 0.01)." (PMID 35464946, 2022). "Despite comparable levels of IL-10 serum levels in Br group and bm/br4 group at day 6 pci, Br mice succumbed to the infection, while the bm/br4 group survived." (PMID 35719355, 2022). "Notably, mice in Th1 polarised settings (including IL-4 deficient or IL-10/IL-4 double-deficient mice) exhibit rapid weight loss at the onset of egg production, elevated expression of proinflammatory Th1 cytokines and mediators, and high levels of mortality between wks 8-10 of infection." (PMID 35958580, 2022). "IFNγ can be produced by T helper 1 (Th1) cells and increases the cell-mediated response during an infection, but can be counteracted by IL-10 that has an anti-inflammatory and immune suppressive effect." (PMID 36641993, 2022). "In the case of IL-10 production after VSV-infection, EGb decreased the level of this cytokine in AD patients from MedIL−10−α;ControlPBLs+VSV; before=43.49 pg/mL to MedIL−10−α;ControlPBLs+VSV; after=2.37 pg/mL." (PMID 35631163, 2022). "IL-10, an anti-inflammatory factor, is used during infection to reduce tissue damage and immunopathology through suppressing pro-inflammatory responses induced with the aid of diverse immune cells." (PMID 35463642, 2022).
infection (continued). "Together, these data show multiple sources of IL-10 active during H. polygyrus infection and demonstrate high IL-10 expression at the site of infection, in the SILP." (PMID 35428872, 2022). "Violin plots show that Kp52145 infection increased the levels of the M(Kp) markers arg1, il10, chi3l1, ido, pparγ, mrc1, nos2, isg56 and il1rn (Fig EV5A–E)." (PMID 36337046, 2022). "Following infection, the increased expression of IL-10 further inhibits the activity of Th1 cells, NK cells, and macrophages which are crucial for pathogen clearance." (PMID 35109868, 2022). "During infection, NK cells are one of the main sources of IL-10, and AhR activation is required for maximal IL-10 production." (PMID 36110860, 2022). "On the other hand, a smaller number of CD4+ICOS+Foxp3+ cells and reduced amount of IL-10 were observed during the infection with P. chabaudi and P. yoelii 17XNL." (PMID 35109868, 2022). "Using the Py 17XNL model of infection, IL-10 was recently shown to act within the first 4 days p.i. to promote humoral immunity." (PMID 35631044, 2022). "Increased IL-10-producing T cells due to IL-27 was found to enhance survival during infection with viruses such as IAV, RSV, and SeV by attenuating immune cell infiltration, cytokine production, and inflammation." (PMID 35634328, 2022). "Many different immune cells produce the immune suppressive cytokine IL10 contributing to the re-establishment of immune homeostasis after an infection." (PMID 36293090, 2022). "In conclusion, the higher level of effective T-cell response with IFN-γ, IL-17A, and IL-21 contributes to resolved infection outcome, while higher levels of suppressive T-cell response with IL-10 result in HBV chronicity." (PMID 35464946, 2022). "The results showed that at the initial stage of infection, the expression levels of intestinal inflammatory factors such as IL-1β, IL-6, IL-10, TGF-β and TNF-α in the treatment group were much lower than those in the challenge group (p < 0.01)." (PMID 36431853, 2022). "The production level of IL-12 and IFN-γ downregulates while the level of IL-4 and IL-10 upregulates during the infection of Leishmania parasites." (PMID 35734580, 2022). "Previous studies reported higher levels of expression of il-10 that lasted for 3 days’ post-infection." (PMID 35328519, 2022). "The results showed that the levels of IL-4, IFN-γ, and TNF-α increased, and IL-10 decreased after infection with T. gondii." (PMID 36245502, 2022). "Some researchers believe that anti-inflammatory cytokine IL-10 can reduce the intensity of inflammatory response in severe infection." (PMID 36198724, 2022). "The genes assessed in the current study related to inflammation; IFN-y, Il-8, Il-10, are cytokines that are involved in the innate and adaptive immune response and control the response of T-cells after an infection." (PMID 36641993, 2022). "In contrast, AMΦ from BALB/c mice showed higher production of NO, TNF-α, and IL-10 after 7 days of intratracheal infection." (PMID 36520787, 2022). "First of all, compared to the wildtype MYXV infection-triggered response, ΔM062R infection seems to specifically downregulate the immunosuppressive pathways including IL10 and IL4/IL13 pathways, as revealed by both REACTOME and GO analysis." (PMID 36103568, 2022). "IL-10 is primarily known as an anti-inflammatory cytokine: in the face of infection, IL-10 primarily inhibits the host immune response to pathogens." (PMID 35874678, 2022). "IL‐10 is known to act as a double‐edged sword during infection as it acts based on the body's feedback." (PMID 36176597, 2022). "We also found that in splenic T cells of WT mice, infection obviously upregulated Th2 cytokines such as IL-4, IL-10, and IL-13." (PMID 35666747, 2022). "The presence of IL-10 during the first 21 days of M.tb infection has a long-term effect on the control of the infection." (PMID 36189368, 2022).
infection (continued). "Cytokine analysis also showed an increased expression of IL-10 during Py 17XL infection indicating an immunosuppressive mechanism against excessive proinflammation." (PMID 35625397, 2022). "Pure galactan failed to activate naive lymphocytes but induced IL-10 release by bovine macrophages, thus echoing the observation of peak IL-10 1–2 weeks after experimental infection of cattle with M. mycoides subsp." (PMID 35495700, 2022). "The placental microenvironment is rich in IL-10, an anti-inflammatory cytokine that contributes to maternal–fetal tolerance, which can facilitate infection by T. gondii, as shown in this study." (PMID 34135407, 2021). "A three-fold increase in the number as well as the frequency of IL-10 secreting B1a B cell in the splenocytes was noticed following infection with SbR-BHU138 strain compared to uninfected mice." (PMID 34209841, 2021). "The observed transient reductions in the level of anti-inflammatory cytokines, especially IL-10, are in line with our efforts to fine-tune the anti-inflammatory signaling during the establishment of infection, instead of abrogating it permanently." (PMID 34777338, 2021). "The cytokine analysis revealed a significant increase in the level of serum IL-6, IL-10 and IFN-γ during the acute phase of the infection, but interestingly IL-10 lowered to normal upon clearance of the virus in the clinically recovered case." (PMID 34460819, 2021). "In contrast, a slight IL-4 trigger was observed soon after the infection in the 106 group, while IL-6 and IL-10 increased around two to 10-fold." (PMID 34276650, 2021). "This aligns with studies that have shown that reduced expression of IL-1 and IL-10 can exacerbate mental illness or psychotic episodes following infection with CHIKV." (PMID 34358063, 2021). "Thiacloprid led to elevated expression of IL-2, IL-4, IL-10 and downregulated the expression of IgE in mice with secondary infection of AE, and ABZ exerted a consistent effect." (PMID 34488852, 2021). "Increased TNF-α and IL-10 production followed in vitro infection of BMDMs with whole parasites (blue bars)." (PMID 33912181, 2021). "proposes a biphasic effect of IL-10 during infection wherein IL-10 released early in infection inhibits viral neuraminidase enzymatic function." (PMID 33680987, 2021). "Infection with either of the four strains resulted in an up-regulation of IL-6, IL-10, IFN-λ, IFN-γ, IP-10, MX-2, and TNF-α expression in the range of 10- to 1000-fold compared to non-infected hamsters." (PMID 34049240, 2021). "For this purpose, microbiota-depleted IL-10−/− mice were orally infected with C. jejuni strain 81–176 and subjected to cardamom essential oil (EO) via the drinking water starting on day 2 post-infection." (PMID 33466708, 2021). "Very recently, the secondary abiotic IL-10−/− mouse infection and inflammation model has been proven suitable also to unravel C. coli-host interactions." (PMID 34070972, 2021). "For CQ treatment, levels of pro-inflammatory cytokines TNF-α, IFN-γ, IL-10 and IL-4 were also decreased significantly after infection (to 12.0, 25.0, 9.0, and 1.5 times that in controls, respectively)." (PMID 33803419, 2021). "The expression levels of Tgfb, Il10, and Pdl1 also decreased after ME7 infection: For Tgfb, from 9.9% in the control to 7.1% in ME7-infected mice; for Il10, from 3.2% to 2.2% after infection; and for Pdl1 from 2.7% to 1.7% after infection." (PMID 33671884, 2021). "IL-10, a cytokine with antiinflammatory properties, plays a central role in infection by limiting the immune response to pathogens, thereby preventing damage to the host." (PMID 35071278, 2021). "As such, zymosan is now considered a suppressive molecule that increases immune tolerance via maintaining high levels of IL-10 cytokine during infection." (PMID 33572768, 2021).
infection (continued). "In summary, IFNγ/IL10 inversely correlates with the immunological load of infection in an in vitro system, in septic mice and when comparing bacteremic and non-bacteremic critically ill patients." (PMID 33767693, 2021). "For anti-inflammatory factors, the mRNA expression level of IL-10 reached the minimum value after infection with A. hydrophila." (PMID 34220849, 2021). "In this study, IL-10 levels in the control group were higher than in the experimental group on the 7th day after infection." (PMID 33717108, 2021). "During LCMV Cl 13 infection, IL-10-producing, virus-specific CD4+ T cells significantly increase in the spleen and the liver." (PMID 34696381, 2021). "Differences between viral strains included the presence of “Interleukin-10 signaling” in the Afg09 samples; upregulated early in infection and then downregulated starting at 5 DPC." (PMID 34615921, 2021). "Among other functions, IL-10 is also stimulatory towards TCD8+ cells, and this can be associated with the decrease in the CFUs at 60 days post-infection in CD18low mice." (PMID 33796477, 2021). "Alterations at the splenic cytokines, including decreased IFN-γ levels and increased TNF-α and IL-10, were observed after 19 days of infection." (PMID 34575795, 2021). "The key highlights of MAP virulence focus on genes such as the PE/PPE—PGRS family, mycobacterial protein kinases (PknG) and the modulation of IL-12/IL-10 switch during infection." (PMID 34946224, 2021). "Minimal differences were detected for monocyte chemoattractant protein 1 (MCP-1), RANTES, IL-2, IFN-γ, IL-10, IL-12(p40), and IL-12(p70), except during primary infection with D39Δ1098 and D39ΔproB." (PMID 33875471, 2021). "Our previous studies have shown that EgPSC infection or its derived ESPs can elevate IL-10 production in splenic B cells and increase the percentage of Bregs in vivo and in vitro, respectively." (PMID 34552973, 2021). "A significantly higher level of IL-10 in CD18low mice was observed at 15 days post-infection in comparison to WT mice." (PMID 33796477, 2021). "We have extended this knowledge, providing evidence that neutrophils are the main myeloid cell source of IL-10 in response to S. pneumoniae after 48 h of infection." (PMID 33995357, 2021). "The cytokine levels in natural course of infection have been investigated in a number of studied and IL-6, IL-10, TNF-α and IFN-γ were found to be major cytokines during the natural course of infection." (PMID 34851958, 2021). "The role of IL10 in the swIAV infection is unclear but the early production of this cytokine was reported in the lungs of swIAV singly-infected pigs or swIAV and PRRSV co-infected pigs." (PMID 33917103, 2021). "The differences in NLRP3 inflammasome following infection with different Chlamydia species have been documented, suggesting that IL-10−/− has a specific effect on NLRP3-mediated apoptosis." (PMID 34093535, 2021). "We investigated this by performing experimental infection studies in an epithelial cell culture and the secondary abiotic IL-10−/− mouse model." (PMID 33935732, 2021). "Despite M2 markers, the infection of these macrophages with Mtb demonstrated an atypical profile of response, with poor control of infection and similar release of immune mediators, such as IL-10, IL-1β, and TNF-α." (PMID 33921194, 2021). "This is in stark contrast to the well‐established role of IL‐10 in promoting chronicity of infections with the related parasite Leishmania spp.,189 which predominantly infects professional antigen‐presenting cells." (PMID 32799361, 2021). "Many cell types are able to secrete IL‐10 and the major source of IL‐10 is varying depending on the stage of infection (acute or chronic)." (PMID 33421352, 2021). "Over the years, evidence has shown that microbes such as fungi, bacteria and viruses can regulate the host cell IL-10 expression that would allow persistent infection." (PMID 33809042, 2021).